IL1B (interleukin 1 beta)
Diseases named in the same sentence as IL1B in open-access papers (continued):
Sharing a sentence is not in itself a finding about the gene and the disease.
infection (continued). "However, synergistic effects of IL-1β and TNF-α (IL-1β+TNF-α) seemed to be significant for which substantial increases in phosphorylation of IκBα and p65 can be detected as early as 3h post infection." (PMID 26367131, 2015). "B1a B cells were present in equal amount in uninfected C57BL/6J or Il-1b-/- mice suggesting that absence of IL-1β affects the infection-induced expansion of these cells, not their homeostasis." (PMID 25768794, 2015). "In comparison to previous expression studies from our population, genes encoding mediators of the inflammatory response exhibited an elevated expression of inflammatory cytokines such as TNFα, IL-1β, and MIP-1α in fundic and pyloric abomasa 7 days post infection." (PMID 25803687, 2015). "A careful dissection of the transcription profile by day 1 pi in tissues from E75CV1-infected pigs, allowed the confirmation of the significant up-regulation of CD163, IL-1β, IFN-γ, IL-5, IL-6, IL-10, IL-12p40, TNF-α and TGF-βR1 and the down-regulation of DEFB2, immediately after E75CV1 infection." (PMID 26589145, 2015). "Although both cytokines are produced during infection with Ft LVS, Il-1b-/-, but not Il-1a-/-, mice were found to be more susceptible than C57BL/6J mice to Ft LVS infection." (PMID 25768794, 2015). "Moreover, cytokine levels, including interleukin (IL)-1β and IL-6, were reduced in the supernatants following RV14 infection." (PMID 26462747, 2015). "The peak of IL-1β expression was at 2 h in EP infection, but not until 12 h in S. mitis infection, but over the course of infection, the levels of this cytokine were similar in both cases." (PMID 26171605, 2015). "This is further supported by the lack of induction of IL6 and IL1β, major NFkβ targets, whose expression was significantly repressed during infection with Mtb-H rather than Mtb-A." (PMID 24743303, 2014). "Interestingly, the exchange of NS segments also modifies the host antiviral response, as demonstrated by an increase in IL-1β production in both FPV NS- GD and -VN infected chickens, as early as 2 days after infection." (PMID 24460592, 2014). "Contrary to expectations, the cleavage of precursor IL-1β to its mature form did not require caspase-1 during primary infections within the lung despite being required by bone marrow-derived macrophages exposed to live bacteria." (PMID 25198773, 2014). "However, A/H7N9-infected C57BL/6 mice exhibited higher levels of IL-6, MCP-1, and IL-1β, but lower levels of TNF-α and IFN-γ, than A/H7N9-infected BALB/c mice at day 3 postviral infection." (PMID 24676272, 2014). "In the absence of exogenous Naip2 or Naip5, infection with WT Shigella enhanced the processing of pro-IL-1β into IL-1β p17." (PMID 24516390, 2014). "It is also thought that weak TLR signaling in infection results in a lack of IL-1β production, which is needed to drive Th17 differentiation." (PMID 24740005, 2014). "In the absence of LPS priming, Type II strain-infected BMDMs did not produce IL-1β (data not shown), but low levels of IL-18 were measurable by 6 h (PRU) and 24 h (76K) of infection in an NLRP1 variant-dependent manner." (PMID 24626226, 2014). "Moreover, this coincided with a burst of the pro-inflammatory cytokines IL-1β and TNF-α in early and late stages of infection (day 8 p.i.)." (PMID 25075973, 2014). "Relative to cells that had never been exposed to bacteria, challenge of macrophages with L. pneumophila resulted in high levels of I1α, Il1β, Tnfα and Dusp2 transcripts in both infected (GFP+) and neighboring uninfected (GFP−) populations by 4 hrs post infection." (PMID 25058342, 2014). "The IL-1RI-mediated deleterious role during B. thailandensis infection was due to the action of IL-1β, not IL-1α, although both cytokines are produced during infection." (PMID 25166912, 2014).
infection (continued). "Primary genital C. suis infection of the re-infection group (nine-week-old pigs) resulted in increased secretion of TNF-α, IL-1β, IL-6 and IL-12p40 by PBMC, whereas primo-infection of the infection group (seventeen-week-old animals) decreased the IL-1β, IL-8 and IL-10 secretion by PBMC." (PMID 25252649, 2014). "A previously published study from our laboratory however, reported down-regulation of IL-12p40, IL-8, IL–1β, and CCL-20 mRNA in tracheal tissues at day-1 post-infection, whereas chemokines like MIP-1β, CXCL-13, RANTES and lymphotactin were found to be up-regulated." (PMID 25401327, 2014). "To determine if inflammasomes play a role in IL-1β activation in mφs infected by T. cruzi, we pre-treated the THP-1 mφs with selective inhibitors of inflammasome activation for 2 h and continued the inhibition pressure during the infection period." (PMID 25372293, 2014). "Our studies were done at the protein level, and found that infection did not induce secretion of IL-1β by resident macrophages." (PMID 24416445, 2014). "A detailed measurement of levels of 23 cytokines in the BAL, at 2-day intervals between days-0 to 25 revealed maximal elevation of inflammatory cytokines IL1a, IL1b, IL6, TNFα, IFNγas well as chemokines mKC, Eotaxin, MIP1a, MIP1b and MCP1 during the days 5–9 of infection (Fig-1A & Fig-S1)." (PMID 24505273, 2014). "Since the MAPK/ERK pathway is involved in IL-1β-induced COX-2 expression and PGE2 production, it is reasonable to assume that pretreatments with P1G10 potentially influenced the MAP kinase pathway in vivo after infection by Salmonella." (PMID 24757289, 2014). "Therefore, the effects of W. chondrophila infection upon the expression of the pro-inflammatory cytokines, TNF-α, IL-1α, IL-1β and the chemokine CXCL8 was investigated 24 h post-infection." (PMID 25010668, 2014). "IL-1β levels remained undetectable in plasma from WT, Asc−/− and Nlpr3−/− mice after infection with S. Typhimurium (data not shown)." (PMID 25115174, 2014). "To assess local inflammation and cytokine release during RSV 2-20 infection, we performed immunohistochemistry on lung sections at 4 dpi for detection of IL-1β (data not shown)." (PMID 24558422, 2014). "Nevertheless, the induction of IL-1β does not fully explain how P2X7R contributes to exacerbate the disease progression during MP287/03 Mbv infection." (PMID 24991816, 2014). "From the results presented here, it is not possible to conclude if infection is responsible for the IL-1β, IL-6, or IL-4 cytokine production, or if other environmental or genetic differences are responsible for individual differences in cytokine levels." (PMID 24548288, 2014). "Unlike IL-1β, IL-8, and TNFα, IL-6 transcription was significantly up-regulated 8 h after infection." (PMID 24712747, 2014). "Upon infection with ECTV or VACV, p65 was retained in the cytoplasm following treatment with TNFα or IL-1β, indicating that ECTV could inhibit NF-κB despite the lack of orthologs of M2, K7, B14, A49, and A52." (PMID 25122471, 2014). "Investigations into the cytokine response of naïve fibroblasts to infection with N. caninum found that, after 72 hrs, there was a striking and significant increase in production of IL-6, IL-1β but not TGF-β1." (PMID 24961164, 2014). "However, despite p65 translocation, infection with vv811ΔA49 still prevented the TNF-α- and IL-1β-induced activity of an NF-κB reporter and inhibited the transcription and production of cytokines induced by these agonists." (PMID 24371075, 2014). "Monolayer infection of S. Typhimurium N-15 in the presence of low Fe or high Fe fermentation effluents did not change cytokines expression of IL-1β, IL-6 or IL-8 compared to normal Fe effluent." (PMID 24676135, 2014). "Similarly, we observed up-regulation of IL-6, IL-1β and TNF-α in OA hOBs at peak infection (24 hpi) in our study." (PMID 25407789, 2014).
infection (continued). "Our data showed that IL-1β driven neutrophil recruitment during the first 24 h of infection was mediated by lL-17A, while it became independent of IL-17A at later time points during the exacerbation." (PMID 24918427, 2014). "A T3SS3 inner rod protein BsaK mutant failed to activate caspase-1, revealed higher intracellular counts, reduced cell death and IL-1β secretion during early but not during late macrophage infection compared to the wild-type." (PMID 24626296, 2014). "Of note, viral replication was not altered in IL-1β deficient mice, demonstrating that any effects seen in the absence of IL-1β were not due to differences in the infection rate." (PMID 24918427, 2014). "Also a strong upregulation of the proinflammatory genes COX-2, IL-1β, and TNFα was observed in a monocyte/macrophage cell line of trout (RTS11) in response to an infection with Achlya." (PMID 25088077, 2014). "Treatment with IL-1Ra, and thereby blocking both IL-1α and IL-1β, led to increased viral titers in the initial phase of infection, whereas the absence of IL-1β alone did not affect viral replication." (PMID 24918427, 2014). "Also, significantly increased IL-1β release was detected upon PRRSV infection, and the secreted IL-1β was further increased as the infection progressed, peaking at later time points (48 h)." (PMID 24966466, 2014). "We found that the levels of proinflammatory cytokines, including IL-6, MCP-1, IL-1β, TNF-α, and IFN-γ, increased immediately after infection and peaked on day 3 postviral infection, before returning to their baseline levels about 7–10 days after infection in both mouse strains." (PMID 24676272, 2014). "IL-1β expression is elevated in the CNS during HIV-1, SIV and FIV infections." (PMID 24886384, 2014). "The infection of C57BL/6 and P2X7R−/− BMDMs with H37Rv Mtb caused negligible macrophage death, extracellular release of the bacilli and IL-1β production, which were not influenced by the P2X7R." (PMID 24991816, 2014). "By contrast a lack of IFN-γ, induction of FoxP3+ T cells and increased IL-1β and IL-10 secretion were indicative of progressive infection in Sham vaccinated animals." (PMID 25480162, 2014). "IL-1β mRNA levels are significantly elevated in aged mice as compared to young in the absence of infections." (PMID 24558422, 2014). "Results suggest that heat-killed C. neoformans increased the expression levels of IFN-I, IL-1β and IL-6 in the acute phase of infection and enhanced IL-17A production after 2 h (data not shown)." (PMID 24660033, 2014). "Early induction of IL-1β and TNF-α by rBRSVΔSH in the lungs may have contributed to rapid control of virus replication and, therefore, less inflammation, 6 days after infection." (PMID 24700100, 2014). "As UV-inactivated HCV does not replicate, these observations suggest that hepatic macrophages can produce IL-1β after HCV exposure in a manner independent of direct cell infection." (PMID 23633957, 2013). "In BMDMs with non-infected control (NI) and with the iacP fljB fliC mutant infection, the levels of cytokines IL-18 and IL-1β were not detectable." (PMID 24069357, 2013). "IL-6 was detectable in uninfected colonic tissue; the increase upon infection was however not as marked as that seen for IL-8 and IL-1β." (PMID 23922820, 2013). "This excludes the possibility that the differences in IL1β levels in the lungs are due to an effect of glyburide on the burden of infection in the lungs." (PMID 24147174, 2013). "To assess the expressions of inflammatory cytokines following infection with DM-C, we quantified the amount of representative proinflammatory cytokines, including tumor necrosis factor-alpha (TNF-α), interleukin-1β (IL-1β), and IL-6, in the bronchoalveolar lavage fluid (BALF) of infected mice." (PMID 24098364, 2013). "This study was performed to better characterize the role of NLRP3 in early stages of infection and to determine if administration of IL-1β to Nlrp3−/− mice would bypass the lack of NLRP3 inflammasome." (PMID 24312491, 2013).
infection (continued). "For example, a recent study showed a role for NLRP12 in inflammasome formation and IL-1β/IL-18 maturation in response to a subcutaneous infection with a genetically attenuated strain of Yersinia, but not other activators that engage the NLRP3 inflammasome." (PMID 23577168, 2013). "By contrast to rUSSR-NS PR8, which was not detectable at day 2 and 4 post-infection in the lungs, USSR and 1918 NS1 protein inhibition of type I IFN and IL-1β responses were associated with sustained replication and spread to the lungs." (PMID 23592984, 2013). "Our studies demonstrate that IL-1β is stimulated by HCV within hepatic macrophages in a manner that is independent of actual infection but mediated by phagocytic uptake of virus." (PMID 23633957, 2013). "Moreover, MVAΔIL-1βR increased amounts of bioactive IL-1β compared to MVAwt after infection of human THP-1 cells, as detected using a reporter system that only responds to active and free IL-1β." (PMID 23356675, 2013). "Our data here show that lethal infection also induced higher expression of il-1β on day 7, but not day 3, when compared to nonlethally infected mice." (PMID 23526993, 2013). "In the absence of priming, minimal levels of IL-1β were secreted by WT, Nlrp3−/− and Nlrc4−/− macrophages during infection with WT and Δhly L. monocytogenes." (PMID 24058709, 2013). "Further, in view of the persistent lung inflammation in single IL-1α or IL-1β deficient mice during chronic M. tuberculosis infection, we asked how the absence of IL-1α and/or IL-1β modulated the immune response in the lung after 1–3 months of infection." (PMID 25400917, 2013). "Remarkably, IL-1β is essential to the inflammatory response to infections and is not released via the classical endoplasmic reticulum-Golgi secretory pathway." (PMID 24340123, 2013). "TNF-α and IL-1β were both upregulated during infection of normal CEACAM1-humanized but not significantly in WT mice." (PMID 23935487, 2013). "Cillóniz and coworkers demonstrated robust transcriptional changes of inflammatory response genes, including upregulation of inflammasome genes (e.g., CASP1, IL1B, and NLRP3), in response to H5N1 VN1203 compared to 1918 pandemic influenza virus at day 1 post-infection." (PMID 23895213, 2013). "To clarify how h1 deletion affects caspase-1 activation upon infection by V. parahaemolyticus, we examined the amounts of released IL-1β and IL-18 from the infected BMMs with or without LPS pretreatment." (PMID 23357873, 2013). "Mature IL-1β had increased dramatically in the cornea by 24 h of infection, and this was not significantly affected by lumican deficiency." (PMID 23358433, 2013). "IL1B gene expression was up-regulated in response to infection with all three LPAIV isolates as well, with the greatest gene expression changes in the CK/MD/MinhMa infection at 8.2 fold." (PMID 23521892, 2013). "No significant changes in the level of IL-1β transcripts was observed at either 7 or 14 days post REV-CS strain infection, which was different from the results in this study." (PMID 24358317, 2013). "In addition, inflammatory cytokines such as IL-1β, IL-6, and TNF-α activate coagulation systems in infection, trauma, inflammation, and cancer." (PMID 23874602, 2013). "The secretion of IL-1β after stimulation with non-viable NTHi was significantly reduced tending to no response at all in comparison to infection of RAW with viable NTHi." (PMID 23840534, 2013). "Upon infection with Nme, a robust inflammatory response marked by elevated chemokines KC, MIP-1α and MIP-2 as well as cytokines TNF-α and IL-1β was observed in the nasal tissue of CEACAM1-humanized mice and also, to a significantly lower extent, in wild-type mice." (PMID 23935487, 2013). "However, following infection of alveolar macrophages from TLR-5-/- mice with flagellated salmonella and flagellated PA, IL-1β production was still detectable." (PMID 24312669, 2013).
infection (continued). "Significantly less induction of pro-inflammatory cytokines, TNF-α, IL-6, IL-1β and MCP-1, was found at various time post-infection in ApoE−/− mice; whereas anti-inflammatory cytokine IL-10 was not affected, and IL-12 production was not detectable during infection." (PMID 23977160, 2013). "Even though less pronounced, Nlrc4−/− macrophages also secreted lower levels of IL-1β during infection with WT L. monocytogenes, most likely due to the lack of endogenous L. monocytogenes flagellin recognition by NLRC4." (PMID 24058709, 2013). "Although OBs have been shown to express NLRP-3 required for caspase-1 activation associated with OB death in response to infection, we find that MSU activates NLRP3 in human OBs with no production of pro-IL-1β or IL-1β." (PMID 24456929, 2013). "On the other hand, when cPLA2 was blocked 1 h before the infection by treatment of macrophages with cPLA2 antagonist ATK (gray bars), proinflammatory cytokines TNF-α, IL-1β, and IL-6 were upregulated; furthermore, IL-10 expression was significantly affected when cPLA2 was inhibited." (PMID 23555077, 2013). "M. tuberculosis infected macrophages rapidly transcribed IL-1β mRNA as early as 2 h post-infection (data not shown) and sustained expression until 24 h." (PMID 23849220, 2013). "The lung lesions observed in the absence of both IL-1α and IL-1β were similar to those seen in mice deficient for IL-1R1 or TNF, although confluent necrosis was more pronounced in the absence of TNF 4 weeks post-infection." (PMID 25400917, 2013). "In contrast, ultraviolet-irradiated RV14 did not increase the expression of IL-1β, IL-6, and IL-8 at any time point after infection." (PMID 24303127, 2013). "The other 4 cytokines (TNF-α, IL-1α, IL-1β, and eotaxin) were elevated in non-surviving infected mice only at 48 hours after infection." (PMID 23520553, 2013). "To this end, we found that administration of poly I:C, a TLR3 ligand, to RAG−/− mice throughout the first six weeks of infection, resulted in up-regulation of splenic mRNA for IL-1β, TNF, and CCL2, rather than their down-regulation." (PMID 24130499, 2013). "In case of infection of Ehrlichia muris, another obligate intracellular bacterium in the family of Anaplasmataceae, BMDMs do not induce IL-1β secretion, probably because E. muris resides in endosomal compartments and does not escape into the cytosol." (PMID 22723924, 2012). "IETD treatment did not significantly reduce macrophage death or IL-1β secretion after 8 or 24 hours of infection with KIM5." (PMID 22563435, 2012). "In summary, IL-1β-DsRed fluorescence and EGFP-neutrophil fluorescence signals had similar temporal kinetics as they both increased rapidly by day 1 and then decreased along with the in vivo bioluminescent signals over the 14 day course of infection." (PMID 23209417, 2012). "IL-1β produced from infected cells acts via an autocrine/paracrine mechanism to activate NF-κB/MAP kinase dependent pro-inflammatory cytokines and chemokines to establish an effective immune response for combating infection." (PMID 22295065, 2012). "RSV activates NF-κB during infection; however, the role of NF-κB in controlling IL-1β production during RSV infection has not been examined yet." (PMID 22295065, 2012). "The ability of LUJV to influence the immune response is illustrated in guinea pigs by the finding that, despite the very high viral loads by day 5 PI, pro-inflammatory cytokine/chemokine genes, such as IL-1b and RANTES, were downregulated 2–4-fold early during infection." (PMID 22953019, 2012). "Infection of mice with RUH3023T and A. junii LUH5851 did not cause an increase in inflammatory mediators in serum, except for a 5-fold increase of RANTES and IL-1β levels." (PMID 22347396, 2012).